NUP62 (nucleoporin 62)
Description:
Essential component of the nuclear pore complex. The N-terminal is probably involved in nucleocytoplasmic transport. The C-terminal is involved in protein-protein interaction probably via coiled-coil formation, promotes its association with centrosomes and may function in anchorage of p62 to the pore complex. Plays a role in mitotic cell cycle progression by regulating centrosome segregation, centriole maturation and spindle orientation. It might be involved in protein recruitment to the centrosome after nuclear breakdown.
Synonyms: p62; DKFZp547L134; IBSN; SNDI; MGC841; FLJ20822; FLJ43869
Tractability: PROTAC: ubiquitination databases record sites on it; its protein half-life has been measured.
Gene: Protein-coding gene on chromosome 19 (49,906,825 to 49,929,925, reverse strand). Ensembl gene ENSG00000213024.
Subcellular location: Nucleus, nuclear pore complex; Cytoplasm, cytoskeleton, spindle pole; Nucleus envelope; Cytoplasm, cytoskeleton, microtubule organizing center, centrosome
Subcellular location (Human Protein Atlas): Nuclear membrane; Nucleoplasm
Pathways (Reactome):
Disease: Defective TPR may confer susceptibility towards thyroid papillary carcinoma (TPC); HCMV Early Events; HCMV Late Events; NEP/NS2 Interacts with the Cellular Export Machinery; NS1 Mediated Effects on Host Pathways; Nuclear import of Rev protein; Rev-mediated nuclear export of HIV RNA; SARS-CoV-2 activates/modulates innate and adaptive immune responses; Transport of Ribonucleoproteins into the Host Nucleus; Viral Messenger RNA Synthesis; Vpr-mediated nuclear import of PICs
Metabolism of RNA: Transport of Mature mRNA Derived from an Intronless Transcript; Transport of Mature mRNA derived from an Intron-Containing Transcript; Transport of the SLBP Dependant Mature mRNA; Transport of the SLBP independent Mature mRNA; snRNP Assembly; tRNA processing in the nucleus
Metabolism of proteins: SUMOylation of DNA damage response and repair proteins; SUMOylation of DNA replication proteins; SUMOylation of RNA binding proteins; SUMOylation of SUMOylation proteins; SUMOylation of chromatin organization proteins; SUMOylation of ubiquitinylation proteins
Metabolism: IP3 and IP4 transport between cytosol and nucleus; IP6 and IP7 transport between cytosol and nucleus; IPs transport between nucleus and cytosol; Regulation of Glucokinase by Glucokinase Regulatory Protein
Cell Cycle: Nuclear Pore Complex (NPC) Disassembly; Postmitotic nuclear pore complex (NPC) reformation
Cellular responses to stimuli: Regulation of HSF1-mediated heat shock response
Immune System: ISG15 antiviral mechanism
Gene Ontology:
Molecular function: protein binding; SH2 domain binding; signaling receptor complex adaptor activity; ubiquitin binding; chromatin binding; phospholipid binding; structural constituent of nuclear pore; Hsp70 protein binding; Hsp90 protein binding; PTB domain binding
Biological process: cell surface receptor signaling pathway; centriole assembly; centrosome cycle; mitotic centrosome separation; mitotic metaphase chromosome alignment; negative regulation of apoptotic process; negative regulation of cell population proliferation; negative regulation of programmed cell death; positive regulation of canonical NF-kappaB signal transduction; positive regulation of centriole replication; positive regulation of DNA-templated transcription; positive regulation of mitotic cytokinetic process; positive regulation of mitotic nuclear division; positive regulation of protein localization to centrosome; regulation of mitotic spindle organization; nucleocytoplasmic transport; positive regulation of epidermal growth factor receptor signaling pathway; protein import into nucleus; regulation of Ras protein signal transduction; regulation of signal transduction; RNA export from nucleus; negative regulation of epidermal growth factor receptor signaling pathway; negative regulation of Ras protein signal transduction
Cellular component: centrosome; cytoplasm; Flemming body; mitotic spindle; nuclear envelope; nuclear membrane; nuclear pore; nucleoplasm; ribonucleoprotein complex; spindle pole; nuclear pore central transport channel
Genetic constraint (gnomAD): Loss-of-function variants: 0 observed, 18.9 expected, observed/expected ratio (o/e) 0, 90% interval 0 to 0.16. The upper end of that interval is the gene's LOEUF score, 0.16, which puts it in group 1 of 6, group 1 being the genes least tolerant of losing a copy. Missense variants: 647 observed, 712.12 expected, observed/expected ratio (o/e) 0.91, 90% interval 0.85 to 0.97. Synonymous variants: 305 observed, 313.04 expected, observed/expected ratio (o/e) 0.97, 90% interval 0.89 to 1.07.
Gene-disease validity (ClinGen):
ClinGen rates the evidence that NUP62 causes each of these diseases.
Leigh syndrome (autosomal recessive): Disputed. A progressive neurological disease defined by specific neuropathological features associating brainstem and basal ganglia lesions.
Homologues: Orthologues: macaque NUP62 (97% identical), dog NUP62 (86% identical), rabbit NUP62 (82% identical), rat Nup62 (80% identical), guinea pig NUP62 (80% identical), mouse Nup62 (80% identical), pig NUP62 (75% identical), tropical clawed frog nup62 (53% identical), zebrafish nup62l (50% identical). Paralogues in human: NUP62CL (20% identical).
Diseases named in the same sentence as NUP62 in open-access papers:
NUP62 is named in the same sentence as 61 diseases in open-access papers, as found by Europe PMC text mining. Sharing a sentence is not in itself a finding about the gene and the disease. The quoted sentences say what the papers report.
HIV-1 infection (6 papers, 2012 to 2024). The type species of lentivirus and the etiologic agent of acquired immunodeficiency syndrome (AIDS). "Later proteomics and immunogold electron microscopy studies showed that HIV-1 infection induces extensive changes in the composition of the nuclear envelope and its associated proteins and identified Nup62 as a component of purified virus." (PMID 22928108, 2012). "While the loss of Nup54 and Nup58 elevated infection of WT HIV-1, N74D HIV-1, and P90A HIV-1, removal of Nup62 had a larger positive effect on WT HIV-1 infection." (PMID 37355754, 2023). "By contrast, depletion of Nup62 or Nup214 elevated WT HIV-1 infection, and Nup54 and Nup58 knockdown enhanced infection of both WT and CA mutant HIV-1." (PMID 37355754, 2023). "In contrast to the striking effects on MX2 activity, manipulation of the Nup62 complex had only modest effects on CypA/CsA modulation of HIV-1 infection." (PMID 30084827, 2018). "Adenoviruses increase the permeability of NPCs by displacing Nup214, Nup358 and Nup62 to facilitate nuclear import of its ≈30 Kb genome; HIV-1 infection was shown to induce re-distribution of Nup62 to facilitate nuclear export of its genomic mRNA (reviewed)." (PMID 24084236, 2013). "Removal of Nup62 subcomplex members (Nup54, Nup58, and Nup62), which are FG-Nups that form a meshwork in the central channel of the pore restricting the flow of cargo larger than 5 nm in diameter, generally elevated both WT and N74D HIV-1 infection." (PMID 37355754, 2023). "Notably, knock-down of NUP214, NUP62 or NUP98 had minimal effects (<2-fold) on HIV-1 infection in control cells, indicating that each of these nucleoporins promote MX2 anti-viral function." (PMID 30496303, 2018). "Finally, expression of the C-terminal domain of Nup62 in CD4+ T cells reduced the association of IN with chromatin and did inhibit HIV-1 infection." (PMID 22928108, 2012). "Nup62 knockdown in CD4+ T cells and macrophages significantly inhibited HIV-1 infection and by qPCR analysis, the block of the infection was pinpointed to viral integration and in a much lesser extent to the nuclear import step." (PMID 22928108, 2012). "Of note, Nup62 is translocated to the cytoplasm and encapsidated into HIV-1 virions during HIV-1 infection." (PMID 22928108, 2012). "That manipulation of the Nup62 complex had both positive and negative effects on MX2 activity against HIV-1, without affecting MX2 localization, suggests that it participates in HIV-1 infection." (PMID 30084827, 2018). "In fact, several Nup depletions (NUP205, NUP62, NUP54, and NUPL1) had larger effects on HIV-1 infection in non-dividing as compared to dividing HOS cells." (PMID 30084827, 2018). "HIV-2 and SIVmac infection were inhibited by many Nup depletions and both were modestly sensitive to depletions of a number of Nups that did not affect HIV-1 infection (e.g. NUP155, TPR, NUP62, NUP54, NUPL1." (PMID 30084827, 2018).
amyotrophic lateral sclerosis (4 papers, 2023 to 2024). Amyotrophic lateral sclerosis (ALS) is a neurodegenerative disease characterized by progressive muscular paralysis reflecting degeneration of motor neurons in the primary motor cortex, corticospinal tracts, brainstem and spinal cord. "Emerging research suggests that NUP62 is involved in amyotrophic lateral sclerosis (ALS) and multiple sclerosis." (PMID 39080077, 2024). "Another study reported that depletion and cytoplasmic mislocalization of Nup62 contributes to TDP-43 proteinopathy in amyotrophic lateral sclerosis (ALS)/frontotemporal lobar degeneration (FTLD)." (PMID 36908815, 2023). "NCT and NPC integrity have been found to be compromised in Amyotrophic Lateral Sclerosis (ALS) and other neurodegenerative disorders by the dysregulation of the C-ter structured domain of NUP62." (PMID 39273335, 2024).
Huntington disease (4 papers, 2023 to 2025). Huntington disease (HD) is a rare neurodegenerative disorder of the central nervous system characterized by unwanted choreatic movements, behavioral and psychiatric disturbances and dementia. "Nup62 is also associated with other neurodegenerative diseases, such as Alzheimer’s and Huntington’s disease." (PMID 36908815, 2023). "In Huntington’s disease (HD), Nup62 and other Nups co-aggregate with cytoplasmic mutant Huntingtin in HD patients, iPSC-derived neurons, and mouse models." (PMID 38254150, 2024).
ovarian carcinoma (4 papers, 2012 to 2025). A malignant neoplasm originating from the surface ovarian epithelium. "NUP62 has been associated with autoimmune conditions and ovarian cancer." (PMID 36127808, 2023). "Only NUP62 has been shown to affect drug sensitivity: its knockdown confers cisplatin resistance in ovarian carcinoma cells." (PMID 41153808, 2025). "Western blot analyses revealed that knockdown of NUP62 or NUP214 to ∼25% of control levels resulted from treatment of TOV112D cells (derived from a high grade ovarian carcinoma) with combinations of targeted siRNAs." (PMID 22558357, 2012). "Nup62 overexpression is reported from the prostate, and ovarian cancers, and ROCK1 dependent Nup62 phosphorylation induces p63 nuclear localization and cell proliferation." (PMID 36845732, 2023). "Ovarian carcinoma TOV112D cells and COS7 cells displayed two major populations of NPCs: peripheral rim NUP62+/NUP214− and contralateral surface NUP62−/NUP214+ NPCs, with few NUP62+/NUP214+ NPCs observed." (PMID 22558357, 2012).
Alzheimer disease (3 papers, 2022 to 2025). A progressive, neurodegenerative disease characterized by loss of function and death of nerve cells in several areas of the brain leading to loss of cognitive function such as memory and language. "Similar to ALS, abnormal localization of Gle1, Nup62, and RanGAP1 (the binding partner of Nup358) in multiple models of HD and Nup62 in the hippocampus and neocortex of Alzheimer’s disease patients was previously reported." (PMID 35628261, 2022).
breast carcinoma (3 papers, 2019 to 2026). "Other members of the nucleoporin family have been linked with cancer including Tpr, NUP62, NUP214 and NUP358/RanBP2 with NUP88 and more recently, NUP43 specifically linked to poor outcome in breast cancer." (PMID 30935371, 2019).
glioma (3 papers, 2023 to 2025). A benign or malignant brain and spinal cord tumor that arises from glial cells (astrocytes, oligodendrocytes, ependymal cells). "In glioma (GBMLGG), LGG, HNSC, and LIHC, significant differences in NUP62 expression are found among tumor patients with different G stages." (PMID 40098960, 2025). "The representative results showed WDR82 did not correlate with the expression of NUP62 and FBOX10, genes for which levels increased in pediatric glioma tissue specimens." (PMID 37444539, 2023).
proteinopathy (3 papers, 2022 to 2023). "This suggests that NUP62 mislocalization may be a common pathogenic event that drives TDP-43 proteinopathy across a variety of neurodegenerative disorders." (PMID 35697676, 2022). "Our findings indicate NUP62 cytoplasmic mislocalization contributes to TDP-43 proteinopathy in ALS/FTLD." (PMID 35697676, 2022). "We mainly focused on Nup62, which strongly co-aggregates with TDP-CTF and is recruited into TDP-43 aggregates induced in a seeding model of TDP-43 proteinopathy." (PMID 36482422, 2022). "Our finding that both Nup62 and KPNB1 are recruited to all pTDP-43 inclusions in ALS/FTD patients, strongly supports the relevance of our data from disease models for human TDP-43 proteinopathies." (PMID 36482422, 2022).
brain injury (2 papers, 2021 to 2023). Acute and chronic (see also brain INJURIES, CHRONIC) injuries to the brain, including the cerebral hemispheres, CEREBELLUM, and brain STEM. "(F, G) Adult Drosophila expressing Nup62 RNAi or Nup214 RNAi in neuronal cells exposed to repeated traumatic brain injury (TBI) were raised on RU486 (+ RU486) or ethanol (-RU486) treated food for 20 days before motor assays." (PMID 34060470, 2021). "Drosophila and rat models of traumatic brain injury (TBI) exhibit abnormalities of multiple Nups, including Nup62, as well as RanGAP, and both TBI-induced NCT deficits and lethality in Drosophila can be rescued by treatment with nuclear export inhibitor KPT-350." (PMID 37720544, 2023).
cardiovirus infection (2 papers, 2019 to 2022). "Most importantly, FG-NUPs that had previously been shown to be hyperphosphorylated during cardiovirus infection: NUP62, NUP98, NUP153 and NUP214 exhibited statistical significance." (PMID 36508477, 2022). "For example, enterovirus and cardiovirus infections alter NPC composition to relocalize some nuclear proteins to the cytoplasm, whereas enteroviruses are known to induce degradation of nucleoporins Nup62, Nup98, and Nup153." (PMID 31875556, 2019).
cervical cancer (2 papers, 2009 to 2023). A primary or metastatic malignant neoplasm involving the cervix. "Many of the genes, including BIRC2, BIRC3, ATF5, NUP62, FASTKD3, IDH3G, and POFUTI, have been found to be regulated by gains or losses in previous cervical cancer studies." (PMID 19911042, 2009). "The enriched genes included CD4 in cervical cancer, VPS52, NUP62, CRYGD, IL34, GATA3 in prostate cancer and F11, TXNIP, KIT, ASGR2, SERPINF1 in liver cancer, which also provide insight into the molecular mechanisms underlying cancer progression and the potential impact on patient survival." (PMID 37393582, 2023).
head and neck cancer (2 papers, 2023 to 2024). A primary or metastatic malignant neoplasm affecting the head and neck. "For example, in head and neck cancer, NUP62 plays a role in stabilizing NUP88, which ultimately leads to the activation of the NF-κB pathway, promoting the proliferation of cancer cells." (PMID 38660294, 2024). "Here, we report that Nup88 and Nup62 mRNA and protein levels are elevated in head and neck cancer tissues." (PMID 36845732, 2023). "In conclusion, our data indicates that simultaneous overexpression of Nup62 and Nup88 in head and neck cancer stabilizes Nup88." (PMID 36845732, 2023). "Since Nup88 and Nup62 form stable complexes and their expression levels show alterations in different cancers, we have probed how the expression and interactions of Nup88 and Nup62 correlate with head and neck cancers." (PMID 36845732, 2023). "Here, we report that Nup88 and Nup62 levels are significantly elevated in head and neck cancer patient samples and cell lines." (PMID 36845732, 2023). "We analyzed this co-upregulation of Nup88, and Nup62 in head and neck cancer tissue lysates, and observed that both Nup88 and Nup62 levels were higher in tumor tissues (n=4)." (PMID 36845732, 2023). "Next, we analyzed the expression of Nup62 and Nup88 using the Oncomine database in the Ginos Head and neck cancer statistics." (PMID 36845732, 2023). "Moreover, limited information about the Nup88 and Nup62 expression level changes in various cancers including head and neck cancer impedes our understanding of the process." (PMID 36845732, 2023).
infantile bilateral striatal necrosis (2 papers, 2022). Several syndromes of bilateral symmetric spongy degeneration of the caudate nucleaus, putamen and globus pallidus characterized by developmental regression, choreoathetosis and dystonia progressing to spastic quadriparesis. "She described how a point mutation in Nup62 (Q391P) causes Infantile Bilateral Striatal Necrosis (IBSN), a syndrome that has overlapping features with ANE, but is considered distinct." (PMID 35485383, 2022).
ischemia (2 papers, 2019 to 2023). A hypoperfusion of the BLOOD through an organ or tissue caused by a PATHOLOGIC CONSTRICTION or obstruction of its BLOOD VESSELS, or an absence of BLOOD CIRCULATION. "DIM also reduced protein levels of autophagy-related BECN1 and LC3, partially reversed the ischemia-induced decrease in NUP62 and inhibited autophagosome formation." (PMID 30778709, 2019).
lupus (2 papers, 2021 to 2022). "These included anti-complement 3 (lupus), anti-complement C1q (lupus), anti-SP100 (lupus), PR-3 (vasculitis), anti-LC-1 (autoimmune hepatitis), anti-Nup62 (primary biliary cirrhosis), anti-MI-2 (myositis), and anti-vimentin (rheumatoid arthritis)." (PMID 33897700, 2021).
neuroblastoma (2 papers, 2012 to 2026). Neuroblastoma (NB) is the most common solid, extracranial childhood tumor. "The S12 neuroblastoma cell line was chosen for this analysis as it displays each of the three permutations of NUP62/NUP214 immunolabeled NPC types." (PMID 22558357, 2012). "Instead, higher levels of NUP62, NUP93, and NUP98 were correlated with mortality, high-risk, advanced stages of International Neuroblastoma Staging System (INSS), or disease progression in 498 NB patients (GSE62564), and associated with worse survival outcome." (PMID 41510169, 2026).
Parkinson disease (2 papers, 2023 to 2025). A progressive degenerative disorder of the central nervous system characterized by loss of dopamine producing neurons in the substantia nigra and the presence of Lewy bodies in the substantia nigra and locus coeruleus. "It has been shown that overexpression of miR-133a inhibits MPP+-induced autophagy (MAP1LC3A/MAP1LC3B, BECN1, NUP62) in a cellular model of Parkinson’s disease, and downregulation of miR-17-5p inhibits infarction-induced myocardial autophagy." (PMID 36324052, 2023).
rheumatoid arthritis (2 papers, 2021 to 2025). A chronic, systemic autoimmune disorder characterized by inflammation in the synovial membranes and articular surfaces. "Furthermore, changes in Nup62 function and levels are related to various age-related diseases including cancer, neurological diseases and rheumatoid arthritis." (PMID 39891615, 2025).
viral infection (2 papers, 2024 to 2025). "The presence of both RACK1 and PKCα/β is required for the phosphorylation of NUP62 and suppression of antiviral gene expression, thereby benefiting virus infection." (PMID 39602452, 2024). "Concurrently, the phosphorylation of NUP62 decreased to nearly undetectable levels in both mock- and IBV-infected cells, highlighting the essential role of PKCα/β in NUP62 phosphorylation under normal physiological conditions and during viral infection." (PMID 39602452, 2024).
ciliopathies (1 paper, 2023). "Despite an accumulation of evidence highlighting the roles of NUP62 and NUP98 in cilia, there are as yet no direct indications from human diseases or model organisms to establish a clear link between NUP62/98 and ciliopathies." (PMID 37908226, 2023).